AXL (AXL receptor tyrosine kinase)
Diseases named in the same sentence as AXL in open-access papers (continued):
Sharing a sentence is not in itself a finding about the gene and the disease.
infection (95 papers, 2013 to 2025). The state of being infected such as from the introduction of a foreign agent such as serum, vaccine, antigenic substance or organism. "The in-vitro experimental results support the in-silico prediction but indicate that AXL expression is specifically associated with infection by the BCoV/Resp isolate." (PMID 39941096, 2025). "Here we demonstrate that ablation of AXL enhances the susceptibility to infection by influenza A virus and West Nile virus." (PMID 27350258, 2016). "Furthermore, we isolated a ZIKV mutant that bypasses the AXL-dependent mechanism for infection of these cells and then mapped the mutation to the pr region of the prM gene." (PMID 40062839, 2025). "Concurrently, these particular cell type's infections are linked to higher AXL protein levels." (PMID 38675970, 2024). "Finally, strong correlations of AXL expression on monocytes with disease severity and prognosis, that is, i.e. development of infection, episodes of AD, and 1-yr mortality underline its clinical significance." (PMID 31822557, 2020). "Furthermore, infection of primary human cells or cell lines that are susceptible to flaviviruses, such as astrocytes or epithelial cell lines, relies on AXL endogenous expression, because antibodies against this receptor strongly block DENV infection." (PMID 24381034, 2013). "Furthermore, analysis of flaviviral entry receptor expression showed that FRPEs had higher levels of AXL, heat shock proteins, and integrins as compared to iRSCs, which may explain the differential susceptibility to infection in these cell types." (PMID 36680182, 2023). "We found that AXL-mediated SFTSV infection utilizes the bridging action of growth arrest-specific protein 6 between AXL and phosphatidylserine on virus particles." (PMID 40853130, 2025). "To validate the GeCKO library sequencing results, we generated SNB-19 cells with AXL KO and subjected them to infection by the ZIKV PRV (ZIKV PRVABC59) isolate of ZIKV or DENV-2 (D2-16681)." (PMID 40062839, 2025). "Recent studies have revealed the presence of PS on the envelopes of various viruses, including Lassa, Ebola, dengue, and Zika viruses, and demonstrated AXL’s involvement in these infections (17, –, 25)." (PMID 40853130, 2025). "Optimal levels of infection within the skin required expression of the phosphatidylserine receptor, AXL." (PMID 40938099, 2025). "Passage of ZIKV in AXL knockout (KO) cells generated a mutant virus capable of infection via AXL-independent mechanisms, and multiple independent selections identified a common mutation, H83R, in the prM coding region of the ZIKV genome." (PMID 40062839, 2025). "Treatment with the anti-AXL antibody neutralized infection in a dose-dependent manner, suggesting that SFTSV utilizes AXL for entry into HUVECs." (PMID 40853130, 2025). "Using a surrogate EBOV model, we demonstrate that systemic infection can occur following topical administration through abraded skin and requires phosphatidylserine receptor, AXL, for optimal infection of skin." (PMID 40938099, 2025). "This reduced susceptibility to SFTSV occurred despite similar levels of AXL expression on the cell surface and GAS6 binding capacities, suggesting that the kinase activity of AXL participates in SFTSV infection." (PMID 40853130, 2025). "At 24 h post-infection with either Wuhan or Omicron strains, the levels of AXL and PROM1 were unaffected." (PMID 40659811, 2025). "We noted that ZIKV does increase the expression of AXL at 2 h, but we noted a reduction over the time course of post infection." (PMID 41373653, 2025). "In this study, we find that the exogenous administration of PROS1 mitigates lung injury and protects mice from lethal infection by IAVs through the activation of AXL." (PMID 41158072, 2025). "Further work with ZIKV found that sequestration of Gas6 by an AXL decoy receptor inhibited infection." (PMID 40062839, 2025).
infection (continued). "SARS-CoV-2 activated the PI3K/Akt/mTOR signaling during the initial phases of infection, which supported the theory of AXL as an early warning indicator for clinical deterioration." (PMID 38799467, 2024). "For instance, in vitro has shown that the infection of glial cells by ZIKV is inhibited by the inhibition of AXL." (PMID 38675970, 2024). "The high p24 detected in their CD11c+ AXL+ DCs was due to infection by HIV-1 (NL-AD8) in the presence of Vpx, thus neutralising SAMHD1." (PMID 38924030, 2024). "The expression of AXL in astrocytes-hNS1 is consistent with reports showing that infection in astrocytes is mediated by AXL." (PMID 36989308, 2023). "The proteomics and Luminex data showed that various macrophage and neutrophil related cytokines and chemokines like MCP-1, IP-10 (CXCL10), MIG, MIP-1β (CCL4), CXCL8 (IL-8), SAA2, and AXL were dramatically upregulated at 7 days after infection." (PMID 35903092, 2022). "At the same time, clinical data from patients with SARS-CoV-2 also show that the expression level of AXL is highly correlated with severe infections." (PMID 35450063, 2022). "Protein S in serum is also dispensable in AXL-induced SARS-CoV-2 virus pseudotype infection, as evaluated by using serum-free media." (PMID 33420426, 2021). "In previous studies, ZIKV hijacked AXL to antagonize the type I interferon pathway to promote its infection, and the deficiency in Ifnar just weakened the need of ZIKV for AXL." (PMID 33954117, 2021). "The effect of P. gingivalis LPS infection on AXL expression in hPDLCs was attenuated by the miR-34a inhibitor." (PMID 34734092, 2021). "In contrast, inhibition of AXL modestly reduces the infection of ZIKV, suggesting its secondary contribution in placental cells." (PMID 33954117, 2021). "Soluble human ACE2 and AXL blocked SARS-CoV-2 virus pseudotype infection in cells overexpressing ACE2 and AXL, respectively." (PMID 33420426, 2021). "Taken together, the data presented here demonstrate that SARS-CoV-2 utilizes AXL to enhance infection in some human lung cell lines, and that this mechanism can be effectively disrupted in by small molecule inhibitors or genetic ablation of AXL." (PMID 34797899, 2021). "In this regard, it is interesting to note that AXL has been reported to be a receptor mediating the infection of multiple virus, such as West Nile virus, Zika virus and SARS-CoV-2." (PMID 34439388, 2021). "c) Is AXL a common receptor for all flaviviruses, and does AXL perform other functions during flavivirus-infection?" (PMID 33954117, 2021). "AXL down-regulation in ACE2-KO H1299 cells was shown to significantly reduce SARS-CoV-2 pseudotyped infections." (PMID 34867819, 2021). "Overexpression of AXL in HEK293T cells greatly increased the number of SARS-CoV-2 virus pseudotype particles at 24 h post infection." (PMID 33420426, 2021). "Downregulation of AXL in ACE2-KO H1299 cells still significantly reduced SARS-CoV-2 virus pseudotype infection, indicating that AXL-mediated SARS-CoV-2 entry is ACE2-independent." (PMID 33420426, 2021). "This indicated that the intracellular kinase region of AXL was essential for infection of DENV but dispensable for viral entry." (PMID 33954117, 2021). "The results showed that the expression levels of GAS6 and AXL decreased after P. gingivalis LPS infection." (PMID 34734092, 2021). "To assess the role of AXL in the related betacoronavirus, mouse hepatitis virus (MHV strain A59), we investigated the ability of bemcentinib to inhibit infection in C57BL/6J mouse bone marrow derived macrophages (BMDMs) that express AXL." (PMID 34797899, 2021). "Of note, AXL sufficient MΦ promoted enhanced glycolysis to compensate for the energy demands needed for sustaining the pro-inflammatory state in response to infection induced inflammatory stimuli." (PMID 34372552, 2021).
infection (continued). "SARS-CoV-2 virus pseudotype particles were observed on the surfaces of HEK293T cells overexpressing AXL at 2 h post infection, indicating that AXL facilitates SARS-CoV-2 virus pseudotype binding to the cell surface." (PMID 33420426, 2021). "In contrast, the prostate and seminal vesicles are protected from infection, which is consistent with the distribution of AXL." (PMID 33954117, 2021). "For example, ectopic expression of TYRO3 and AXL enhances infection of all DENV serotypes, as well as other related viruses such as WNV and YFV." (PMID 32172658, 2020). "Actually, a preprint publication suggests an interaction of AXL with SARS-CoV2 promoting infection in epithelial cells." (PMID 32998369, 2020). "TIM-1, which is abundant on Th-2 T cells, mucosal epithelial cells, and mast cells, mediates the attachment of ZIKV particles on the cell surface to facilitate their interaction with AXL as well as the subsequent infection." (PMID 31866959, 2019). "When we studied this receptor, AXL showed a significantly higher expression one day after infection in placenta cells when compared to uninfected cells; however, those expression levels returned to normal within three days after infection." (PMID 30453684, 2018). "Conversely, infection of in vitro-derived fetal neural progenitor cells appears to be AXL-independent." (PMID 30453621, 2018). "Exposure to neutralizing antibody against AXL or by gene silencing using small interfering RNA targeting the AXL gene led to a decrease in viral replication and infection, suggesting a role of AXL as a putative ZIKV entry receptor in human fibroblast cells." (PMID 30374352, 2018). "In contrast, siRNA against STAT2 in infected placenta cells significantly induced AXL expression after three days of infection when compared to control cells." (PMID 30453684, 2018). "Our previous work also found that GAS6 and its receptor AXL are expressed in arteries of the gingival lamina propria, while repetitive infections with P. gingivalis down-modulate their expression and prevents innate inflammation." (PMID 29967614, 2018). "Take together, these results indicate that the ablation of AXL in myeloid cells is sufficient to confer susceptibility to IAV infection and that preserved expression in DCs appears to be required to resist the infection." (PMID 27350258, 2016). "BMDCs derived from Cd11c-Cre+Axlfl/fl recapitulated the increased resistance to PR8-GFP infection characteristic of Axl-/- BMDCs, confirming the functional ablation of AXL in this line." (PMID 27350258, 2016). "We previously demonstrated that infection of Huh-7 cells with HCV (JFH1 strain) induces the expression of AXL as well as its downstream target SOCS3." (PMID 26313459, 2015). "Because HCV induces oxidative stress, inflammation, and a strong type III immune response in the liver, it is not surprising that the activation of these transcription factors following infection in vitro induced AXL expression." (PMID 26313459, 2015). "TYRO3 and AXL ectopic expression enhances infection by all DENV serotypes, as well as by the related WNV and YFV." (PMID 24381034, 2013). "In addition to angiotensin-converting enzyme 2 (ACE2) and neuropilin-1 (NRP1), AXL acts as a spike protein receptor and mediates infection, especially in respiratory cells with low ACE2 expression." (PMID 40649848, 2025). "While the Y821A mutation in AXL did not affect SFTSV infection, consistent with the previous reports on Ebola virus and Lassa virus, the Y779/821A double mutation in AXL significantly reduced susceptibility to SFTSV, likely due to a loss of PI3K interaction." (PMID 40853130, 2025). "Interestingly, POWV (M11665) showed significantly higher levels of infection in AXL- and TIM-1-expressing cells—approximately 4-fold (p < 0.01) and 7-fold (p < 0.0001), respectively—compared to WT cells." (PMID 41358161, 2025).
infection (continued). "Quantitative analysis revealed a high degree of similarity between the proteins in the mock and virus-infected groups, with AXL being the only protein identified as significantly enriched in the infected group, based on a threshold of P.adjust ≤ 0.05 and fold change (infection/control) ≥2." (PMID 40277356, 2025). "Given the broad tissue distribution of AXL, surpassing that of DC-SIGN and including key cell types such as fibroblasts and Langerhans cells in the skin, the primary sites for vector-borne viral entry, AXL emerges as a primary receptor for SFTSV in the early stages of infection." (PMID 40853130, 2025). "Indeed, continued passaging of AXL KO cells exposed to ZIKV PRV generated a mutant virus, designated as 1ZS3, which achieved a much higher infection rate than the WT virus in the AXL KO cells while retaining similar infection efficiency in the WT SNB-19 cells." (PMID 40062839, 2025). "However, Y779- and Y821-independent AXL-mediated SFTSV infection was completely suppressed by the treatment with PI3K or PLC inhibitors." (PMID 40853130, 2025). "Treatment with U73122, a PLC inhibitor, significantly reduced SFTSV infection of HEK293AXL and HEK293AXL-Y779/821A but not of HEK293AXL-Y866A, indicating that AXL-Y866A mutation inhibits SFTSV infection due to loss of PLC binding." (PMID 40853130, 2025). "Bemcentinib was optimized to specifically target the human protein AXL, therefore, the anticancer/Bemcentinib combination could be simultaneously beneficial for infection and improving cisplatin's effects on cancerous cells." (PMID 38501485, 2024). "The electrostatic potential energy map predicted the susceptibility of bovines to cross-species infection by SARS-CoV-2 and also whether ACE2, AXL, and NRP1 proteins might serve as potential receptors for SARS-CoV-2." (PMID 38012648, 2023). "The infection of SARS-CoV-2 could be significantly inhibited by AXL protein at a concentration of 25 μg/ml." (PMID 35277473, 2022). "Our data indicate that AXL serves as the most important PS receptor for SARS-CoV-2 infection of the TIM and TAM families and our studies with MHV implicated AXL in facilitating infection of additional coronaviruses." (PMID 34797899, 2021). "GAS6 does not bind SARS-CoV-2 or promote AXL-induced SARS-CoV-2 virus pseudotype infection." (PMID 33420426, 2021). "Besides their role during the course of infection with the intracellular parasite L. major, AXL and MERTK expression has been also detected during the inflammatory response induced by the helminth parasite Nippostrongylus brasiliensis (N. brasiliensis)." (PMID 34279684, 2021). "We determined the expression of AXL in A549 cells with CD147 KD or mock KD and found that high levels of AXL were expressed in both lines, suggesting that AXL may contribute to the infection of CD147 KD cells." (PMID 34064066, 2021). "We surmise that AXL-inhibiting therapeutics could function in tandem with other antivirals, protecting a number of organs from infection." (PMID 34797899, 2021). "The occurrence of AXL-expressing monocytes was independent of the underlying aetiology and other potential confounders (inpatient treatment, current infection, antimicrobial treatment, immunosuppressive therapy, and non-metastatic malignancies)." (PMID 31822557, 2020). "Overall, our data clearly indicate that ZIKV-infection of HBVP is dependent on AXL and GAS6." (PMID 32357162, 2020). "To assess whether AXL receptor mediates ZIKV entry and infection, we treated fcMSCs (n = 4) with AXL blocking antibody for 1 h prior to infection with ZIKV 1 MOI for 6 h." (PMID 32941515, 2020). "Here we assessed if the AXL protein plays a role in the productive infection of pericytes." (PMID 32357162, 2020). "For example, inhibiting AXL function can protect cells from infection and, thus, may be a potential target for the production of entry inhibitors." (PMID 31866959, 2019).
infection (continued). "Furthermore, the observation that antibody- or drug-mediated blocking of AXL significantly reduces infection of HFAs is consistent with findings from others supporting a role for AXL as an entry receptor on astrocytes." (PMID 30453621, 2018). "Indeed, ZIKV productively infected both HESC and T-HESC, whereas in vitro decidualization of the cell line (dT-HESC) increased both the expression of putative ZIKV entry co-receptor AXL and the levels of productive infection vs. unstimulated cells." (PMID 28281680, 2017). "Indeed, blocking of two of these receptors, TIM and tyrosine-protein kinase receptor UFO (AXL), or of PS itself blocks efficient infection with picornaviruses." (PMID 28976939, 2017). "To monitor whether USUV is using these proteins to infect astrocytes, we performed a competition experiment by pre-incubating cells with either anti-AXL or anti-DC-SIGN antibodies prior to infection with USUV or ZIKV." (PMID 28873445, 2017). "Our results support the hypothesis of a prominent role of AXL in infection of HESC and a potential deleterious role of progesterone in favoring virus transmission to the trophoblasts, in case of pregnancy, or during sexual intercourse with an infected partner." (PMID 28281680, 2017). "In vitro experiments have led to the speculation that AXL promotes the infection of several enveloped viruses including vaccinia, Lassa, dengue, and WNV." (PMID 27350258, 2016). "Nevertheless, a study indicated that AXL could independently mediate the omicron infection." (PMID 38799467, 2024). "So, while AXL expression correlates well with macrophage infection, its prominent role as an entry receptor is less supported by the rather low infection rate of myofibrocytes, although this cell type might not be directly accessible to the virus at the beginning of infection." (PMID 37350967, 2023). "However, anti-AXL siRNA was able to inhibit ZIKV in HT1080 cells assessed at 24 h post-infection." (PMID 35126336, 2021). "Additionally, these findings also support previous studies that both implicate AXL as a host cell receptor for Asian/American ZIKV strains and those that show genetically ablated animals are still susceptible to infection by establishing two distinct binding mechanisms for this clade." (PMID 31795144, 2019). "Thus, examining the differential affinity displayed by different isolates in binding to the AXL/Gas6 viral entry receptor(s) may help to further elucidate the mechanism by which the contemporary strains elicit increased infection kinetics." (PMID 30572570, 2018). "We tested whether GW4869 decreases AXL, thus dampening the infection in astrocytes." (PMID 29707233, 2018). "During the initial stages of infection, ZIKV interacts with host cell surface receptors such as AXL, which not only promotes viral entry but also suppresses host Type I IFN response." (PMID 40573410, 2025). "The sTIM1dMLDR801 reagent is capable of competitively blocking PtdSer-dependent infection of enveloped viruses mediated by PtdSer-recognizing receptors such as TIM-1, TIM-4, and AXL." (PMID 41358161, 2025). "The results from RT-qPCR analysis at 24 hpi showed that in Vero E6 cells, the soluble TIM-1 receptor neutralized infection for all tested viruses, demonstrating that TIM-1 and AXL are important entry receptors for PtdSer-dependent infection of POWV and DTV." (PMID 41358161, 2025). "D2-Y98P infected AXL KO and WT SNB-19 cells with near equal efficiency, while ZIKVFSS infection of AXL KO cells was dramatically reduced as compared to that of WT cells." (PMID 40062839, 2025). "In HEK293AXL/GAS6KD cells, the addition of recombinant GAS6 restored SFTSV infection in a dose-dependent manner, highlighting an essential role of GAS6 in AXL-mediated viral entry." (PMID 40853130, 2025). "The study illustrated the overall profile of serum ACE2, AXL, SARS-COV-2 IgG/IgM at different time points after infection." (PMID 38799467, 2024).